INS (insulin)
Diseases named in the same sentence as INS in open-access papers (continued):
Sharing a sentence is not in itself a finding about the gene and the disease.
Hyperglycemia (continued). "It is usually associated with hyperglycemia and dehydration, and is typically managed with dedicated protocols that call for aggressive rehydration and insulin administration in an attempt to correct the acid–base imbalance." (PMID 34631141, 2021). "Hyperglycemia due to sarcopenic obesity causes the glycosylation of several circulating macromolecules, such as albumin, lipoproteins, insulin and hemoglobin." (PMID 33919368, 2021). "AGI drugs can reduce the amounts of insulin needed to control postprandial hyperglycemia by slowing down the digestion of complex carbohydrates and sucrose, therefore it is suitable for the insulin-deficient characteristic." (PMID 34276555, 2021). "Type 1 diabetes (T1DM) is a chronic disease characterized by hyperglycemia due to a deficiency in endogenous insulin production, resulting from pancreatic beta cell death." (PMID 33911129, 2021). "Our results show that the Domeless receptor loss in fat body cells reverses both hyperglycemia and the increase in the expression of the insulin resistance marker Nlaz, observed in larvae fed a high sugar diet." (PMID 33547367, 2021). "Being physically active with T1D increases an individual’s risk of activity-related hypoglycemia and hyperglycemia, and fear of activity-related hypoglycemia has often been a deterrent of regular participation for insulin users of all ages." (PMID 34501920, 2021). "Diabetes mellitus is a group of metabolic disorder characterized by hyperglycemia, caused by defects in insulin secretion, action, or both." (PMID 33668369, 2021). "Management is challenging because high energy and nutritional requirements are needed to support growth, and variable insulin sensitivity makes infants at risk from both hyperglycaemia and hypoglycaemia." (PMID 33577770, 2021). "Alloxan is a diabetogenic agent that destroys the islets of Langerhans, resulting from a massive reduction in insulin release, causing hyperglycemia (2016)." (PMID 34401085, 2021). "Evidence supports the notion that NPY plays an important role in inhibiting insulin secretion, causing hyperglycemia in mice." (PMID 33708805, 2021). "We found that circulating osteocalcin was inversely correlated with glycemia: it was lower in those with stress hyperglycemia, those in need for insulin infusion therapy, and also associated with longer ICU stays." (PMID 34578888, 2021). "Although insulin was reported to exert anti-inflammatory effects in patients with moderate degree of hyperglycemia, it was simultaneously associated with refractory poor glucose control and was not protective against hospitalization due to infection." (PMID 34552886, 2021). "Lastly, there is a need for further research with regard to improving insulin sensitivity in the interconception period and consequently lowering the risk of recurrence of hyperglycemia in high-risk patients with a history of GDM." (PMID 34682918, 2021). "As a confirmation of implication of the sympathetic system activation, the use of α2 or β-adrenergic receptor antagonist with clozapine was able to reverse hyperglycemia and reduce insulin secretion caused by clozapine." (PMID 33800403, 2021). "T2DM is a metabolic disease characterized by long-term hyperglycemia caused by potential metabolic dysfunctions, such as IR of muscle and liver tissues and decreased insulin secretion by pancreatic β-cells." (PMID 34740995, 2021). "As the first phase of insulin secretion is lost in T2DM, second phase insulin secretion is further impaired, causing postprandial hyperglycemia, which serves as an early marker of T2DM progression." (PMID 34071359, 2021). "Elevated blood glucose levels and diet can stimulate pancreatic β-cells to produce insulin, which is bound by IAA, thereby rendering insulin ineffective, forming a "reservoir" and causing postprandial hyperglycemia." (PMID 33827670, 2021).
Hyperglycemia (continued). "Glucocorticoids cause hyperglycemia by increasing glucose resistance, decreasing insulin secretion, inducing beta cell apoptosis, and reducing the expression of glucose transporters." (PMID 34198724, 2021). "The failure of pancreatic beta cells to produce insulin, and the impairment of insulin action, play a central role in the disruption of glycemic homeostasis, leading to hyperglycemia, a hallmark of DM (Thomas and Philipson., 2015)." (PMID 34955862, 2021). "Metreleptin was shown to reduce hyperphagia leading to weight loss, to improve insulin sensitivity and secretion, to reduce hypertriglyceridemia, hyperglycemia, and fatty liver disease in many patients with lipoatrophic diabetes." (PMID 34342583, 2021). "DM is a chronic metabolic disorder characterized by hyperglycemia which is caused by deficiency of insulin secretion, insulin action, or both." (PMID 34335803, 2021). "The reduction of insulin secretion is the cause of high blood glucose levels, which is a characteristic of hyperglycemia." (PMID 34371645, 2021). "The activation of the SNS also causes the inhibition of glucose-stimulated insulin secretion and the increase of glucagon secretion via the α-receptor, caused hyperglycemia." (PMID 34805193, 2021). "The results indicated that hyperinsulinemia or hyperglycemia induced by intravenous infusion of glucose or insulin caused minimal net uptake of glucose by the liver (~4%–14%) despite marked stimulation of total glucose turnover." (PMID 33419065, 2021). "In this syndrome, an increase in glucagon secretion and a decrease in insulin secretion occur, which cause hyperglycemia and the development of dehydration." (PMID 34912875, 2021). "High glucose levels increase the risks of hyperglycemia, including reduced insulin secretion, and limit the enteral feedings; hyperglycemia is associated with an increased incidence and severity of ROP." (PMID 34444915, 2021). "TID is a well-known cause of secondary osteoporosis, and the pathogenesis of fracture seems to be multifactorial, depending on hyperglycemia, insulin/IGF-1 deficiency, hypogonadism, kidney disease, and vitamin D deficiency." (PMID 32915436, 2021). "EMC-D virus can infect and destroy beta-cells of the pancreas in mice and cause hyperglycemia dependent on insulin." (PMID 34429169, 2021). "Several randomized studies have shown that MP is associated with a higher incidence of hyperglycemia which needs treatment with insulin." (PMID 34631828, 2021). "It stated that when TNF-α was amplified, the insulin effect was diminished causing intensification of hyperglycemia, and thereby augmented the impact of NF-κB proteins." (PMID 34922513, 2021). "Deletion of β-catenin in exocrine tissue was also associated with fasting hyperglycemia, in addition to lower rates of glucose clearance and insulin sensitivity." (PMID 34568323, 2021). "By contrast, when the fetus has inherited the maternal mutation, treatment of maternal hyperglycemia should be avoided because of the risk of fetal growth restriction due to a decrease of fetal blood glucose values under the insulin secretion threshold." (PMID 35069449, 2021). "Prolonged hyperglycemia (670G only), max/min insulin delivery, loss of CGM data, sensor integrity concerns, lack of calibrations." (PMID 33996702, 2021). "Absolute deficiency of insulin action causes severe hyperglycaemia due to unrestrained liver glucose output and impaired peripheral glucose disposal." (PMID 34841432, 2021). "Increased fasting glucose levels are a result of stress hyperglycemia, which is caused by the interplay of hormones, with concomitant insulin resistance during acute illness." (PMID 34122311, 2021). "Women with a history of GDM exhibited lower insulin sensitivity and subtle impairments in β-cell function associated with subclinical hyperglycemia already at the beginning of a subsequent pregnancy compared to women without GDM history." (PMID 34682918, 2021).
Hyperglycemia (continued). "An increase in the plasma levels of insulin that is associated with hyperglycemia is also observed in patients treated with PI3K inhibitors and hence enhanced insulin level serves as a pharmacodynamics surrogate marker for such patients." (PMID 33801659, 2021). "This study aimed at assessing the associations between neonatal hyperglycaemia and insulin treatment, and neurodevelopmental outcomes at 6.5 years of age in children born EPT." (PMID 33863775, 2021). "SGLT-2 inhibitors increase the glucose excretion to lower hyperglycemia, which is a unique insulin-independent mode of action with a limited risk of hyperglycemia." (PMID 34744998, 2021). "T2D is a complex clinical syndrome characterized by persistent hyperglycemia, associated with decreased insulin secretion and sensitivity." (PMID 33973089, 2021). "Inside the beta cells, streptozotocin cases DNA alkylation, which results in loss of cellular function and prompt decrease in insulin levels leading to hyperglycemia." (PMID 34371877, 2021). "We would take the view that these findings represent reverse causation—whereby those with severe illness require insulin to treat stress hyperglycaemia." (PMID 34268452, 2021). "The greater risk of drug-induced hyperglycemia and DM with pasireotide likely results from impaired insulin and incretin secretion, with a minor effect on glucagon production." (PMID 33079318, 2021). "Cola drinking caused impaired glucose tolerance as well as fasting hyperglycemia (mean:148; CI:137–153; p<0.05 vs W) and an increase of in insulin immunolabeling (27.3±19.7; p<0.05 vs W and L)." (PMID 34115756, 2021). "Hyperglycemia and dysfunctional insulin signaling have been associated, in peripheral organs, with increased levels of O-GlcNAcylated proteins." (PMID 33916835, 2021). "The report adds, “Use of organization-approved protocols for insulin and other glucose-lowering medications can help reduce therapeutic inertia and/or reduce the risk of hypoglycemia and hyperglycemia”." (PMID 34434951, 2021). "In T2DM, hyperglycemia is caused by long-term excessive hepatic gluconeogenesis, decreased insulin activity, low peripheral glucose uptake, and changes in insulin signaling." (PMID 34485159, 2021). "Alloxan is a cytotoxic glycoside and acts as a diabetogenic by the annihilation of the islets of Langerhans and causes an enormous decline in insulin discharge, thus prompting hyperglycemia." (PMID 33897432, 2021). "Once the β cells are dysfunctional, the body cannot produce enough insulin to maintain the stability of blood glucose, and long-term hyperglycemia of the body will cause multiple organ dysfunction." (PMID 34194388, 2021). "This irreversible loss of insulin-producing β cells impairs crucial glucose uptake in peripheral tissues, resulting in hyperglycemia and subsequent life-threatening microvascular and macrovascular complications." (PMID 34447354, 2021). "A tentative association between Covid-19 and hyperglycemia has been suggested; the profound inflammatory activation occurring with Covid-19 has been proposed to be associated with decreased insulin secretion and increased insulin resistance." (PMID 33466617, 2021). "Progressive degradation of pancreatic β-cells causing reduced insulin production and subsequent hyperglycemia is observed in all types of T1DM." (PMID 34833905, 2021). "Catecholamines have been shown to directly suppress insulin secretion from the pancreas, causing glycogenolysis in the liver by stimulating the α-adrenergic receptor and ultimately causing hyperglycemia." (PMID 34488743, 2021). "Amino acids stimulate insulin secretion, and low plasma arginine levels have been associated with hyperglycaemia." (PMID 34368024, 2021). "Chronic hyperglycemia causes an increased metabolic demand towards the β-cells, which undergo compensatory insulin hypersecretion to maintain normoglycemia." (PMID 33918509, 2021).
Hyperglycemia (continued). "In critically ill humans with sepsis, tight glucose regulation using insulin to manage disease-associated hyperglycemia has been commonly practiced." (PMID 33763464, 2021). "Taken together, our study revealed insulin resistance as the direct cause of hyperglycemia upon COVID-19, and further illustrated the underlying mechanisms, providing potential therapeutic targets for COVID-19-induced metabolic complications." (PMID 34916489, 2021). "In MS patients, the capacity of insulin to inhibit glucose production is reduced, resulting in mild hyperglycemia, which in turn stimulates insulin secretion, causing a state of hyperinsulinemia." (PMID 34069012, 2021). "More importantly, Lepvv treatment partially normalized the reduction in insulin concentrations and hyperglycemia associated with T1D." (PMID 34947993, 2021). "NSO increases PARP-γ in the adipocyte and inhibits an enzyme that degrades insulin considered a cause of hyperglycemia." (PMID 34833928, 2021). "Otherwise, the persistent chronic exposure of the newly formed β cells to insulin resistance, glucotoxicity and lipotoxicity would likely cause failure of the new β-like cells, with recurrence of hyperglycemia." (PMID 34882233, 2021). "After adjusting the model for confounding variables, patients with hyperglycaemia treated with an insulin infusion had a lower risk of complications than patients who did not receive an insulin infusion." (PMID 33063540, 2021). "After 4 weeks of intervention, insulin alone or combined with curcumin was able to significantly reduce hyperglycemia (p < 0.01) and weight loss (p < 0.01) in diabetic rats, in addition to improving polyphagia, polydipsia, and polyuria." (PMID 34955862, 2021). "DBP is shown to cause hyperglycemia in Drosophila male flies by disrupting conserved insulin and glucagon-like signaling." (PMID 34395617, 2021). "Hyperglycaemia is one of the most frequent side effects of PN and can be limited by adding insulin, which reduces the risk when PN administration has to be stopped, unlike with Y-site infusion or subcutaneous injection." (PMID 33801784, 2021). "Insulin is an important regulator of glucose homeostasis, and the loss of this vital hormone results in hyperglycemia and the pathologies associated with T1DM." (PMID 33800470, 2021). "T2DM is a chronic metabolic disorder characterized by persistent hyperglycemia caused by impaired insulin secretion or tissue insulin insensitivity to peripheral actions of insulin, or both." (PMID 34121170, 2021). "For example, homozygous CLOCK mutant-obese mice exhibited hyperlipidemia, hepatic steatosis and hyperglycemia and insufficient compensatory insulin production (a hallmark of type 2 diabetes mellitus)." (PMID 34943809, 2021). "An earlier study that used an intramuscular injection of rAAV-lep produced circulating leptin levels of 2–5 ng/mL and was capable of reducing food intake, body weight, hyperglycemia and insulin levels in leptin-deficient ob/ob mice for a 6-month period." (PMID 34947993, 2021). "In summary, we found that hyperglycaemia is prevalent during CF exacerbations, appears to improve with exacerbation treatment but to recur later in association with a decrease in insulin secretion." (PMID 33855211, 2021). "Defective action of insulin in peripheral tissues causes a reduced insulin-mediated glucose uptake in skeletal muscle, resulting in persistent hyperglycemia, and enhances lipolysis in adipose tissue, with increased levels of free fatty acids." (PMID 34201382, 2021). "Hyperglycaemia is prevalent during paediatric CF exacerbations; it appears to improve with exacerbation treatment but to worsen later in association with decreased insulin secretion." (PMID 33855211, 2021). "It is only when pancreatic β-cell’s capacity is overwhelmed and insulin secretion fails—via either loss of β-cell function or mass (discussed later)—that overt hyperglycemia and T2D ensue." (PMID 34943836, 2021).
Hyperglycemia (continued). "Overexpression of the GR in pancreatic beta cells leads to reduced insulin secretion associated with an impaired glucose tolerance and eventually hyperglycaemia." (PMID 33805856, 2021). "Type 1 diabetes (T1DM) is a chronic autoimmune disease characterized by hyperglycemia caused by a deficiency in endogenous insulin production as a consequence of pancreatic beta cell death." (PMID 33911129, 2021). "In animal models, increased levels of resistin induced hyperglycemia associated with elevated hepatic glucose production while the reduction in resistin prevents obesity-related hyperglycemia due to increased insulin sensitivity." (PMID 34202323, 2021). "Insulin is recommended as first-line treatment for hyperglycemia in GDM by the ADA and many other associations." (PMID 34579668, 2021). "Some agents targeting the PI3K/Akt signaling pathway are associated with hyperglycemia due to interaction with the insulin-glucose regulatory axis." (PMID 34804943, 2021). "Sirolimus has been shown to cause dose-dependent hyperglycemia and to reduce insulin sensitivity in the short term." (PMID 33808901, 2021). "In support of this, it has been shown that taurine decreases hyperglycemia, insulin loss and mitochondrial oxidative stress, as well as hormone-associated changes through the inhibition of the hypothalamic-pituitary-gonadal axis." (PMID 36699147, 2021). "First, hyperglycaemia is common, occurring in 21–37% of the patients and is probably caused by the secreted catecholamines that inhibit insulin secretion and increase insulin resistance." (PMID 34170845, 2021). "The two reported cases presented with severe hyperglycaemia and weight loss with notably elevated insulin, C-peptide and triglyceride levels." (PMID 34803927, 2021). "As the disease progresses, resultant insulin deficiency and hyperglycaemia necessitates insulin therapy in many cases." (PMID 33950566, 2021). "In illnesses associated with hyperglycemia risk, since the diabetics on an insulin pump use rapid or short-acting insulin, through it they are more prone to DKA if the acute illness is not addressed in a timely manner." (PMID 34873537, 2021). "A neurogenic differentiation factor 1 (NEUROD1) gene mutation causes beta-cells dysfunction, inadequate insulin secretion, and hyperglycaemia (MODY 6)." (PMID 34654408, 2021). "Insulin omission causes hyperglycaemia, which can lead to several vascular complications associated with increased morbidity and mortality." (PMID 34121470, 2021). "T2DM is characterized by hyperglycemia, decreased glucose tolerance, and insulin resistance and hyperlipidemia, and is caused by the inefficient use of insulin." (PMID 34441595, 2021). "Stress hyperglycemia is mediated by pro-inflammatory cytokines that cause a stress response with excessive gluconeogenesis, glycogenolysis, and insulin resistance." (PMID 34768603, 2021). "T1DM, which is also considered insulin-dependent diabetes, occurs when insulin is insufficient and causes hyperglycemia in young patients." (PMID 33849514, 2021). "This enhanced and almost restored early insulin secretion after Whey pre-load is important since a deficiency or loss of this early insulin response is a key abnormality contributing to hyperglycemia and T2D." (PMID 34063109, 2021). "The disease is characterized by chronic hyperglycemia, caused by defects in the insulin secretion or action pathway." (PMID 34944640, 2021). "In this study, the disorder of pancreas β-cell by STZ induction caused poor insulin secretion and then hyperglycemia occurred." (PMID 32399477, 2020). "Results from prandial changes and glucose tolerance test suggested that Ad-feed intake to 45 weeks impaired insulin secretion and glucose clearance, and, thus, caused hyperglycemia in accompany with transient hyperinsulinemia at age of 33 weeks (p < 0.05)." (PMID 33114772, 2020).